VHL (von Hippel-Lindau tumor suppressor)
Diseases named in the same sentence as VHL in open-access papers (continued):
Sharing a sentence is not in itself a finding about the gene and the disease.
neuroendocrine tumors (18 papers, 2009 to 2026). "In humans, hereditary germline mutations and mutations in the von Hippel-Lindau (VHL) gene lead to the development of multiple neuroendocrine tumors including PCs." (PMID 30176869, 2018). "von Hippel-Lindau (VHL) disease, an autosomal dominant inherited disorder resulting from mutations in the VHL gene, is known to be associated with the development of neuroendocrine tumors (NET) in various organs, including the adrenal gland, pancreas, and paraganglion." (PMID 41948715, 2026). "Patients with SCAs and VHL mutations may actually have a mixed serous-neuroendocrine tumor." (PMID 38068358, 2023). "VHL-related pancreatic pathology encompasses true cysts (serous cysts), serous cystadenomas, and neuroendocrine tumors (VHL-pNET)." (PMID 40989257, 2025). "Pdxp gene expression is increased in murine hepatic stellate cells cultured in hypoxia, in VHL-deficient murine endothelial fibroblasts and in neuroendocrine tumors lacking Siah2, a ubiquitin ligase that modulates HIF stability." (PMID 35251031, 2022). "In addition, VHL patients often require multiple operations to manage non-neuroendocrine tumors that develop in other organs." (PMID 35951216, 2022). "Long-term clinical follow-up include genetic background analysis such as SDHB, SDHD, VHL, and RET, required in view of the metastatic potential of this rare neuroendocrine tumor." (PMID 41426338, 2025). "Even though this study focuses on the regulation of HIF2α by VHL in another context, it shows that high levels of HIF2α is not compatible with neuroendocrine tumor cell fitness." (PMID 41118218, 2025). "F76del mutant was selected because represents the VHL gene alteration (c.227_229delTCT) associated with a wide spectrum of cancers including PGLs and no-neuroendocrine neoplasms related to VHL disease." (PMID 28036268, 2017).
ovarian carcinoma (18 papers, 2012 to 2025). A malignant neoplasm originating from the surface ovarian epithelium. "For instance, in ovarian cancer, exosomes derived from cancer-associated adipocytes have been shown to promote tumor angiogenesis and metastasis by transferring miR-199a-5p, which targets the Von Hippel-Lindau (VHL) and Notch1 genes." (PMID 39866229, 2025). "Genomic analysis of the ovarian-carcinoma A1847 cells resistant to CRBN- or VHL-recruiting PROTACs, revealed the amplification of the ABCB1 gene associated with increased expression of mRNA and protein." (PMID 36986673, 2023). "Molecular investigations indicated that MIR210HG directly targets HIF-1α and inhibits VHL-dependent HIF-1α degradation in ovarian cancer." (PMID 34900667, 2021). "Knockdown of VHL also efficiently blocked shMIR210HG-mediated HIF-1α reduction in ovarian cancer cells, which suggested that MIR210HG regulates HIF-1α expression in a VHL-dependent manner." (PMID 34900667, 2021). "Molecular investigations indicated that MIR210HG directly targets HIF-1α protein and inhibits VHL-dependent HIF-1α protein degradation in ovarian cancer." (PMID 34900667, 2021). "Ginsenoside Rg3 has also been shown to increase the expression of tumor suppressor von Hippel-Lindau (VHL) gene in ovarian cancer cells via suppressing DNMT3A expression and thus downregulating the DNA methylation level of the VHL promoter." (PMID 34950039, 2021). "Mechanistically, GHET1 interacted with VHL, the E3 ubiquitin ligase of HIF1α, which blocked the binding between VHL and HIF1α in ovarian cancer cells." (PMID 30988076, 2019). "Of note, GHET1 was found to interact with the E3 ubiquitin ligase von Hippel-Lindau (VHL), which consequently blocked VHL-mediated degradation of hypoxia-inducible factor-1α (HIF1α) and enhanced the protein level of HIF1α in ovarian cancer cells." (PMID 30988076, 2019). "Overexpression of GHET1 promoted the glycolysis of ovarian cancer cells via modulating VHL-mediated degradation of HIF1α." (PMID 30988076, 2019). "The molecular study uncovered that GHET1 interacted with VHL and blocked the binding between VHL and HIF1α, which led to the stabilization of HIF1α and up-regulation of glycolysis of ovarian cancer cells." (PMID 30988076, 2019). "In the present study, we identified GHET1 as a novel binding partner of VHL, which consequently promoted the protein stability of HIF1α and enhanced the glucose metabolism of ovarian cancer cells." (PMID 30988076, 2019). "A functional link between defects of the VHL gene and activation of the miR-210 signaling pathway has also been demonstrated in other tumors such as PCCs, ccRCC and ovarian cancer." (PMID 28036268, 2017). "Collectively, these results suggest that 20(S)-Rg3 blocked hypoxia-induced EMT of the ovarian cancer cells by activating the PHD1- VHL- ubiquitin/proteasome pathway to facilitate HIF-1α degradation." (PMID 25197976, 2014). "In addition to these genes, a high risk for ovarian cancer is associated with mutations in the DICER1, VHL, PTCH1, SUFU, SMARCB1, and SMARCA4 genes." (PMID 37685988, 2023). "Thus, we determined the expression of VHL in A2780 and SKOV3 cells and found that lncRNA-MIR210HG had little effect on VHL expression in ovarian cancer cells." (PMID 34900667, 2021). "Furthermore, knockdown of VHL by siVHL transfection also efficiently blocked shMIR210HG-mediated HIF-1α reduction in ovarian cancer cells." (PMID 34900667, 2021). "It has also been proven to directly down-regulate methylation of Von Hippel-Lindau Tumor Suppressor (VHL) or indirectly decrease the expression of HIF-1α through reducing methylation of miR-519a-5p precursor gene by inhibiting the expression of DNMT3A in ovarian cancer cells." (PMID 35774614, 2022). "The first evidence of the resistance to PROTACs was demonstrated in vitro in ovarian-cancer cells exposed to CRBN- and VHL-recruiting PROTACs targeting BET proteins." (PMID 36986673, 2023).
ovarian carcinoma (continued). "In ovarian cancer, gastric carcinoma high expressed transcript 1 (GHET1) interacts with the E3 ubiquitin ligase von Hippel-Lindau (VHL)." (PMID 33652661, 2021). "LncGEHT1 can interact with von Hippel-Lindau (VHL) to block the degradation of HIF-1α, thus modulating lactate production and influencing the growth of ovarian cancer." (PMID 35004308, 2021). "VHL was detected in the immunoprecipitation complex with GHET1, which suggested the interaction between GHET1 and VHL in ovarian cancer cells." (PMID 30988076, 2019).
clear cell carcinoma (16 papers, 2005 to 2026). "Loss of 3p in clear-cell carcinoma targets driver genes of VHL, PBRM1, SETD2 and BAP1 with collateral deletion of a series passenger genes, amongst which certain genes harbor indispensable functions to maintain cancer cell viability." (PMID 34593007, 2021). "For example, the overall VHL mutation frequency decreased from 63.7% (3 exons) to 40.6% (1–2 exons) in all cancers and dropped from 78.3% to 59.3% in clear cell carcinomas." (PMID 32076485, 2020). "The mutation frequency of 59.3% found in these 275 clear cell carcinomas with complete analysis of all 3 VHL exons is likely to represent the “real” prevalence of VHL mutations in our patient cohort." (PMID 32076485, 2020). "Majority of clear cell carcinoma that is 95.23% (except one case), both the cases (100%) of papillary renal cell carcinoma and 75% hybrid tumors showed VHL mutations." (PMID 25097537, 2014). "A frequent finding in the majority of conventional clear cell carcinomas is a mutation in the von Hippel-Lindau (VHL) suppressor gene, the protein product of this gene is required for degradation of hypoxia-inducible factor 1α (HIF-1α)." (PMID 16222313, 2005). "There have been pharmacological triumphs in the treatment of VHL clear cell carcinomas, for example with the HIF2α inhibitor belzutifan." (PMID 39045559, 2024). "To further validate this finding, we generated VHL-KO Caki-1 cells, a human clear cell carcinoma cell line with WT VHL expression." (PMID 39050705, 2024). "Von Hippel Lindau (VHL) gene alterations result in the overexpression of growth factors that are central to the pathogenesis of clear cell carcinoma." (PMID 36765622, 2023). "Up to 92 percent of clear cell carcinoma patients were characteristic of VHL gene mutant, which leads to overproduction of VEGF and then contributes to angiogenesis of ccRCC." (PMID 33665156, 2020). "Overall the data suggest that the vast majority (> 90%) of clear cell carcinomas harbor VHL aberrations." (PMID 32076485, 2020). "These lines were derived from 786-O, a clear-cell carcinoma that contains a deletion and frameshift of the VHL gene." (PMID 15956968, 2005). "The complete lack of an association between 3p deletions and VHL mutations in our 452 clear cell carcinomas with FISH and sequencing data is unexpected, however." (PMID 32076485, 2020). "They do not exhibit gains of chromosome 7 or 17 nor loss of chromosome Y as seen in papillary renal cell carcinoma, nor do they exhibit loss of the chromosome 3p or VHL gene mutations as seen in clear cell carcinoma." (PMID 25709850, 2015).
glioblastoma (16 papers, 2011 to 2025). The most malignant astrocytic tumor (WHO grade IV). "However, there are also several key genes linked to glioblastomas that don’t exhibit mutations, such as the gene that encodes the Von Hippel Landau protein (or VHL for short)." (PMID 29053101, 2017). "Mechanistically, we revealed that FBXO22 stimulates the activation of the HIF-1α-VEGFA pathway by directly binding and mediating VHL ubiquitination degradation and promoting the malignant progression of glioblastoma." (PMID 38519492, 2024). "Except SKCM, C15 also contained one glioblastoma multiforme cell line (LN229) with low level of VHL and high expression of has-miR-146a, has-miR-29b and has-miR-188-3p (Aurich, Fleming & Thiele, 2017)." (PMID 32874774, 2020). "Two cell lines (U87 and MDA-MB-468) derived from glioblastoma and breast adenocarcinoma were used and both have wild-type VHL as determined by sequencing." (PMID 24563687, 2014). "Since ID2 can prevent proteasomal degradation of HIF-2α in glioblastoma cells by binding to VHL protein present in the Cullin ring E3 ubiquitin ligase (CRL) complex, we examined whether ID2 could inhibit HIF-1α degradation in HSCs." (PMID 35775482, 2022). "The experiments show that glioblastoma cells have lower levels of VHL compared to normal cells." (PMID 29053101, 2017). "Recent studies have highlighted VHL-deficient RCC and IDH1 mutant glioblastoma as particular genetic settings in which tumors may depend on GLS." (PMID 25502225, 2014). "Given that VHL is specifically sensitive to oxygen concentration changes, PTEN-HIF-1α-VEGF pathway was shown to mainly mediate glioblastoma cells’ response to starved conditions." (PMID 23391506, 2012).
bladder cancer (15 papers, 2014 to 2024). "In patients with the VHL mutation, other types of tumors (cervical carcinoma and bladder cancer) were observed in two cases." (PMID 37445575, 2023). "We have previously presented patients with bladder cancer or breast cancer who were positive for heterozygous pathogenic germline VHL variants." (PMID 35774415, 2022). "In a recent study on bladder cancer, differential under-expression of VHL—both mRNA and protein—was found in muscle-invasive bladder cancer in comparison to non-muscle-invasive bladder cancer." (PMID 36036061, 2023). "VHL also was selected for the ligands of E3 ligases, and its high expression in bladder cancer compared to normal tissues was found by comparing TCGA and the human protein atlas database." (PMID 37620295, 2023). "In a recent study on bladder cancer, promoter methylation of the VHL gene was detected in almost 43% of bladder cancer samples, with high methylation being more frequent in muscle-invasive bladder cancer than in non-muscle-invasive bladder cancer." (PMID 36036061, 2023). "Similarly, miR-1826 was reported to play an important role as a tumor suppressor through CNTTB1 and MEK1 in von Hippel–Lindau (VHL)-inactivated renal and bladder cancers." (PMID 32656071, 2020). "Meanwhile, some tumor suppressor genes have been identified as direct and functional targets of miR-155, such as APC, VHL, PIK3R1, MLH1, all of where are frequently inactivated in bladder cancer due to promoter hypermethylation." (PMID 26657502, 2016). "Lastly, tumors whose somatic signature was not consistent with the expected LOH of the VHL gene were likely not component tumors of the VHL disease (e.g., bladder cancer)." (PMID 35774415, 2022). "Having determined variability in the expression of proline-hydroxylated HIF-1α in VHL competent cell lines, we used a panel of tissue microarrays to evaluate the expression of total and proline-hydroxylated HIF-1α in hypoxic head and neck, breast, lung and bladder carcinomas." (PMID 24563687, 2014).
prostate carcinoma (15 papers, 2010 to 2025). A carcinoma that arises from epithelial cells of the prostate gland. "ARCC-4 induces VHL-mediated degradation of AR with a DC50 value of 5 nM in prostate cancer cell lines, effectively reducing AR protein levels." (PMID 40507351, 2025). "PIK5-12d effectivelydegraded PIKfyve with a DC50 value of 1.48 nM and a Dmax value of 97.7% in prostate cancer VCaP cells.Mechanistic studies showed that PIK5-12d induced PIKfyvedegradation through the VHL- and proteasome-dependent manner." (PMID 37605297, 2023). "On the other hand, studies examining a variety of other sporadic tumors, including breast, colon, lung, and prostate cancers, have found that somatic VHL mutations are rare in histological tumor types that are not observed in VHL disease." (PMID 25490036, 2014). "In addition, given the high frequency of VHL mutations in CCRCC, angiogenesis may be much more dependent on VEGF signalling than in prostate cancer, in which multiple redundant pathways have been implicated." (PMID 20648008, 2010). "Takes part in a positive feedback loop to stabilize hypoxia-induced HIF-1α expression. lncRNA-p21 excludes the binding of HIF-1α to VHL (an ubiquitin E3 ligase) in prostate cancer." (PMID 27551267, 2016). "While zinc showed similar effects in prostate cancer under hypoxic conditions, its efficacy was not present in the human RCC4 VHL-null cell line." (PMID 38893207, 2024).
hereditary cancer syndrome (14 papers, 2010 to 2025). "von Hippel–Lindau (VHL) disease is a rare hereditary cancer syndrome caused by germline pathogenic variants in the VHL gene." (PMID 41241877, 2025). "Only 1 out of 6 pathogenetic/likely pathogenetic variants (VHL p.N131T) was from a patient with suspected hereditary cancer syndrome (VHL syndrome)." (PMID 38750555, 2024). "Mutations in VHL cause a hereditary cancer syndrome, and loss of VHL is associated with tumor progression and angiogenesis." (PMID 37563971, 2023). "Mutations in the tumor suppressor gene von Hippel-Lindau (VHL) underlie a hereditary cancer syndrome—VHL disease—and are also frequently observed in sporadic renal cell carcinoma of the clear cell type (ccRCC)." (PMID 27733136, 2016). "von Hippel-Lindau (VHL) disease is a hereditary cancer syndrome caused by germline mutations in the VHL gene." (PMID 20064270, 2010). "Mutation of VHL is reported in von Hippel–Lindau (VHL) hereditary cancer syndrome." (PMID 28861005, 2017). "Further examination of suspected VHL mosaicism is needed to discern the relationship between phenotype severity and mosaicism in this hereditary cancer syndrome." (PMID 35304467, 2022). "A few previous studies have examined the efficacy of PARP inhibition in VHL-deficient RCC cells and in hereditary cancer syndromes using olaparib and BMN-673 (talazoparib)." (PMID 34307148, 2021).
neurofibromatosis type 1 (14 papers, 2012 to 2025). A clinically heterogeneous, neurocutaneous genetic disorder characterized by cafe-au-lait spots, iris Lisch nodules, axillary and inguinal freckling, and multiple neurofibromas. "Genetic syndromes such as multiple endocrine neoplasia type 1 (MEN1), Von Hippel-Lindau (VHL) and neurofibromatosis type 1 (NF1) have been associated with NENs, but they only account for about 10% of observed cases." (PMID 32245472, 2020). "In particular, mutations of VHL, NF1 and RET cause well characterized cancer susceptibility syndrome (von Hippel Lindau, Neurofibromatosis Type 1 and MEN2, respectively)." (PMID 26084817, 2015). "A genetic test for RET, Von Hippel-Lindau (VHL), Neurofibromatosis type 1 (NF1), and of the genes coding for the different subunits of the succinate dehydrogenase (hereditary paraganglioma syndromes) is suggested in familial PCC to obtain a precocious diagnosis." (PMID 24267584, 2013). "However, 10% of PanNETs may occur in hereditary syndromes, such as multiple endocrine neoplasia type 1 (MEN1), Von Hippel—Lindau disease (VHL), type 1 neurofibromatosis (NF1), and tuberous sclerosis complex (TSC)." (PMID 35163032, 2022).
Chuvash polycythemia (13 papers, 2017 to 2025). Chuvash erythrocytosis is a rare, genetic, congenital secondary polycythemia disorder characterized by increased hemoglobin, hematocrit and erythropoietin serum levels and normal oxygen affinity, which usually manifests with headache, dizziness, dyspnea and/or plethora. "Chuvash polycythemia develops with a specific missense mutation in von Hippel–Lindau tumor suppressor (VHL), which reduces its binding to hydroxylated hypoxia inducible factor-α (HIF-α) subunits and increases levels of HIF-1α and HIF-2α." (PMID 38126077, 2023). "These individuals carry homozygous (or, less commonly, compound heterozygous) hypomorphic VHL alleles (Chuvash polycythemia)." (PMID 36106637, 2022). "Individuals with Chuvash polycythemia, with homozygous VHL mutations, for example, develop pulmonary hypertension, as do individuals with activating mutations of HIF2A." (PMID 29569190, 2019). "Certain types of VHL mutations such as loss-of-functions mutation VHLR200W that causes Chuvash polycythemia were described to be causative for poylglobulia." (PMID 30214643, 2018). "Homozygous VHL mutations are implicated in Chuvash polycythemia." (PMID 40130200, 2025). "Furthermore, exposure to acute hypoxia provoked an exaggerated PAP elevation in patients with Chuvash polycythemia and with other VHL mutations." (PMID 33578749, 2021). "Furthermore, a homozygous missense mutation R200W in the VHL gene causes familial erythrocytosis or Chuvash polycythemia, an autosomal recessive disorder endemic to the Russian region of Chuvashia and on the island of Ischia in Italy." (PMID 33578749, 2021). "Other underlying genetic syndromes in patients with PPGL-GN included MEN 4, MEN 2A VHL, NF1, Pacak-Zhuang syndrome, Chuvash polycythemia, and mutations in genes encoding SDH subunits B, C, and D." (PMID 40071066, 2025). "This phenomenon was observed in a subset of patients with familial erythrocytosis type 2 (ECYT2), defined by loss of function of VHL." (PMID 40627222, 2025). "It is also interesting to note that the exercise intolerance noted in Chuvash polycythemia patients is analogous to those seen in skeletal muscle vHL deletion mice." (PMID 29617647, 2018). "Our variant is the third reported Chuvash polycythemia-associated VHL gene variant that does not promote tumorigenesis." (PMID 40130200, 2025). "All reported VHL variants associated with Chuvash polycythemia and lack of malignancy are located at the 3′ end of the gene (both in exon 2 and exon 3), as is our reported p.Ser179Pro variant." (PMID 40130200, 2025). "They found that Chuvash polycythemia-associated VHL variants do not cause the ubiquitin-mediated breakdown of the activated JAK2 protein." (PMID 40130200, 2025).